TRPC1 (transient receptor potential cation channel subfamily C member 1)
Diseases named in the same sentence as TRPC1 in open-access papers (continued):
Sharing a sentence is not in itself a finding about the gene and the disease.
Huntington disease (5 papers, 2014 to 2024). Huntington disease (HD) is a rare neurodegenerative disorder of the central nervous system characterized by unwanted choreatic movements, behavioral and psychiatric disturbances and dementia. "Furthermore, TRPC1 has been shown to be essential for Huntington disease, and mutations in TRPC1 will affect the risk of late-onset AD." (PMID 24852263, 2014). "In Huntington’s disease cell lines, increased calcium influx through TRPC5 causes cell death, whereas, in wild-type cell lines, calcium influx through TRPC5 was reduced when both TRPC1 and TRPC5 formed a heteromeric complex." (PMID 39000357, 2024). "Conversely, TRPC1 has been identified as a promising target for treating Huntington’s Disease (HD)." (PMID 32872338, 2020). "Low levels of TRPC1 increased the formation of homotetrameric TRPC5, a highly Ca2+-permeable channel, and stimulated Ca2+-dependent apoptosis in Huntington’s disease cells." (PMID 30108272, 2018).
nasopharyngeal carcinoma (5 papers, 2014 to 2024). A carcinoma arising from the nasopharyngeal epithelium. "The migratory capacity of nasopharyngeal carcinoma cells is associated with TRPC1 expression, and TRPC1 silencing can decrease cancer cell migration." (PMID 39759147, 2024). "The inhibition of TRPC1 using 2-APB or TRPC1 silencing reduces the adhesive and invasive capabilities of nasopharyngeal cancer cells, suggesting that TRPC1 can modulate metastasis spreading." (PMID 31801263, 2019).
pancreatic cancer (5 papers, 2011 to 2021). "Later, TRPC1 4 and 6 levels were shown to be high in pancreatic cancer cells, indicating their function as TGFβ mediators for Ca2+ entry." (PMID 32046188, 2020). "The role of TRPC1 as a Ca2+ channel in pancreatic cancer cell proliferation and its development was proposed as being a downstream effector of TGFβ signaling." (PMID 32046188, 2020). "In the pancreatic cancer cell line BxPc3, TRPC1 is a transducer of the action of tumor growth factor-β to stimulate cell motility, a process that is of relevance to tumor cell invasion." (PMID 21420431, 2011). "Transforming growth factor β1 (TGF-β1) induces Ca2+ entry likely via TRPC1 and NCX1 that raise cytosolic Ca2+ in pancreatic cancer cells so that knockdown of TRPC1 reverses TGF-β1-induced pancreatic cancer cell motility." (PMID 29772843, 2018).
prostate carcinoma (5 papers, 2019 to 2025). A carcinoma that arises from epithelial cells of the prostate gland. "At the protein level, the immunohistochemical evaluation by the human protein atlas disclosed moderate to high levels of expression for TRPC1 in all prostate cancer samples examined (n = 11)." (PMID 40332161, 2025). "TRPC1 was also robustly expressed in normal prostate, and this may explain the comparative down-regulation observed at the mRNA level in prostate cancer tissues." (PMID 40332161, 2025). "TRPC1 may thus have a certain protective effect against the development of prostate cancer cells." (PMID 33854967, 2021). "Several TRP channels were expressed in prostate cancers at the protein level including TRPM4, TRPML1, TRPML2, TRPC1 and TRPP3." (PMID 40332161, 2025). "In prostate cancer, the expression of TRPC1 was found to be negatively correlated with Ki-67; notably, high expression of TRPC1 prolonged disease-free survival compared with negative TRPC1 expression." (PMID 33854967, 2021). "Resveratrol has been reported to promote autophagy in prostate cancer cells by down-regulating STIM1 and down-regulating SOCE, but the expression of ORAI1 and TRPC1 was not affected during this process." (PMID 31426853, 2019).
triple-negative breast carcinoma (5 papers, 2020 to 2023). An invasive breast carcinoma which is negative for expression of estrogen receptor (ER), progesterone receptor (PR), and human epidermal growth factor receptor 2 (HER2). "Moreover, in triple negative breast cancer, the mesenchymal subtype showed the highest expression level of TRPC1, while the basal subtype with lymph-node metastasis was associated with high TRPC1 expression and worse prognosis." (PMID 34936030, 2021).
breast ductal adenocarcinoma (4 papers, 2012 to 2021). A breast carcinoma arising from the ducts. "Similarly, TRPC1 is more abundant in human breast ductal adenocarcinoma (hBDA), where it has been correlated to proliferative parameters, but not Ca2+ entry." (PMID 23049731, 2012). "Moreover, increased TRPC1 expression was observed in ductal carcinoma cells." (PMID 27793015, 2016). "For instance, increased expression of TRPC1 in human breast ductal adenocarcinoma samples compared to the adjacent non-tumoural tissues strongly correlates with tumour progression and invasion, therefore its silencing suppresses TRPC1-mediated Ca2+ entry and reduces cell proliferation." (PMID 32575381, 2020).
depression (4 papers, 2018 to 2026). "Freichel group showed that heteromeric TRPC1/4/5 channels are involved in depression and anxiety TRPC1/4/5 channels play a role in the development of morphine tolerance and hyperalgesia." (PMID 38384797, 2024). "One of the most researched areas of the role of TRPC1/4/5 channels is their potential involvement in the treatment of anxiety and depression." (PMID 29865154, 2018). "Impairments in the interplay among PSA-NCAM, dopamine D2 receptor, and TRPC1, −4, and −5 may lead to NCAM-and dopamine D2 receptor-associated psychiatric disorders, such as schizophrenia, bipolar disorder, depression, and anxiety disorder." (PMID 36077460, 2022). "Conversely, TRPC1 overexpression mitigates these effects, highlighting its potential as a therapeutic target for post-TBI depression." (PMID 42077357, 2026).
endometriosis (4 papers, 2018 to 2021). The growth of functional endometrial tissue in anatomic sites outside the uterine body. "Moreover, these channels were previously discovered to be somehow involved in several processes that regarded pathogenesis of endometriosis: TRPC1, TRPC4, and TRPV2 are involved in cell migration; TRPC4 in cell adhesion; and TRPM4, TRPM7, and TRPV2 have a crucial role in cell proliferation." (PMID 32046116, 2020). "TRPV2, TRPV4, TRPC1/4, and TRPC6 were expressed in hESC samples retrieved from women affected by endometriosis both at the molecular and functional levels." (PMID 32046116, 2020). "Additionally, TRPV2, TRPV4, TRPC1/4, and TRPC6 were found in human endometrial stromal cells (hESCs) from patients with endometriosis." (PMID 34337010, 2021). "Additionally, and in line with previous reports of control patients, TRPV2, TRPV4, TRPC1/4, and TRPC6 were present in human endometrial stromal cells (hESC) from endometriosis patients both at the molecular and functional level." (PMID 30134548, 2018).
esophageal squamous cell carcinoma (4 papers, 2021 to 2022). Esophageal squamous cell carcinoma (ESCC) is a type of esophageal carcinoma (EC) that can affect any part of the esophagus, but is usually located in the upper or middle third. "In contrast, overexpression of TRPC1 inhibited the proliferation, migration, and invasion of human esophageal squamous cell carcinoma cell line KYSE150 (P<0.01), in a manner at least in part mediated through the AKT/p27 pathway." (PMID 33854967, 2021). "Furthermore, we showed that downregulation of TRPC1 promoted the proliferation, migration, and invasion of human esophageal squamous cell carcinoma cell line EC9706 in vitro." (PMID 33854967, 2021). "Regarding the relationship between TRPC1 and survival in solid cancers, one previous study exhibits that the abnormal expression of TRPC1 is related to poor DFS and OS in esophageal squamous cell carcinoma patients." (PMID 35754147, 2022).
Insulin resistance (4 papers, 2017 to 2025). Increased resistance towards insulin, that is, diminished effectiveness of insulin in reducing blood glucose levels. "Our findings demonstrate that endothelial TRPC1 deficiency exacerbates insulin resistance induced by a high-fat diet and disrupts glucose and lipid metabolism." (PMID 40568618, 2025). "TRPC1/5 has been demonstrated to block adiponectin and create insulin resistance." (PMID 38885005, 2024). "Exercise reduces insulin resistance, but it is not known whether TRPC1 is involved in exercise-induced insulin sensitivity." (PMID 29074621, 2017). "Furthermore, TRPC1 KO mice showed exercise-mediated inhibition of adiposity and decreased insulin resistance in the absence of TRPC1 suggesting that TRPC1 might be the dominant Ca2+ channel in these cells." (PMID 29074621, 2017).
lymph node metastasis (4 papers, 2020 to 2022). "Higher expression rate of TRPC1 was associated with low lymph node metastasis (P<0.001), high differentiation (rs= 0.232, P=0.003), and low Ki-67 (rs = −0.492, P<0.001)." (PMID 33854967, 2021). "Univariate analysis showed that particular status of three variables (lymph node metastasis positivity, poor differentiation, and low TRPC1) were associated with a worse prognosis." (PMID 33854967, 2021). "Further, in TNBC, the mesenchymal subtype showed the highest expression level of TRPC1, and the basal subtype with lymph-node metastasis showed worsened prognoses associated with high TRPC1 expression levels." (PMID 32046188, 2020). "In addition, the findings demonstrated that TRPC1 expression was associated with lymph node metastasis (P<0.001) and differentiation (P=0.028) in this cohort." (PMID 33854967, 2021). "Factors including sex, age, T stage, lymph node metastasis, perineural invasion, differentiation, and the pattern of TRPC1 expression were subjected to univariate and multivariate analyses for DFS and OS." (PMID 33854967, 2021). "The expression of TRPC1 was significantly lower in the group with lymph node metastasis than in the group without lymph node involvement, as well as being lower in the poor-differentiation group than in the medium- or high-differentiation group." (PMID 33854967, 2021). "The expression of TRPC1 in the group with lymph node involvement was significantly lower than that in the group without lymph node metastasis." (PMID 33854967, 2021).
malignant glioma (4 papers, 2016 to 2021). A grade III or grade IV glioma arising from the central nervous system. "In particular, it has been shown that TRPC1 is essential for chemotactic migration in human malignant gliomas in response to chemoattractant growth factors like epidermal growth factor (EGF) and platelet-derived growth factor (PDGF) which affect TRPC1 activity through different signaling pathways." (PMID 33928077, 2021). "Among the TRPCs, TRPC1, and TRPC6 are those for which the mechanism of action has been best characterized in human malignant glioma." (PMID 33928077, 2021).
pancreatic ductal adenocarcinoma (4 papers, 2022 to 2024). An infiltrating adenocarcinoma that arises from the epithelial cells of the pancreas. "Dysregulation of the transient receptor canonical ion channel (TRPC1) has been found in several cancer types, yet the underlying molecular mechanisms through which TRPC1 impacts pancreatic ductal adenocarcinoma (PDAC) cell proliferation are incompletely understood." (PMID 35887266, 2022). "In human pancreatic ductal adenocarcinoma tissue, TRPC1 is abundantly expressed and controls pancreatic ductal adenocarcinoma cell proliferation in a Ca2+ independent way." (PMID 38784033, 2024).
renal carcinoma (4 papers, 2018 to 2022). A carcinoma arising from the epithelium of the renal parenchyma or the renal pelvis. "In order to test these effects of AM237 on endogenous TRPC1:C4 channels, A498 renal carcinoma cells, which endogenously express TRPC1:C4 channels, were pretreated with various concentrations of AM237 before the addition of EA." (PMID 31277085, 2019). "PKCθ and TRPC1:C4 channels (see Section 3.1.1) have been proposed as the relevant target of (−)EA in renal cancer cells, and both proposals were based on extensive experimentation." (PMID 29865154, 2018). "Here, we highlight the use of small-molecule TRPC1/4/5 modulators in the study of specific vulnerabilities of A498 renal carcinoma and SW982 synovial sarcoma cancer cells." (PMID 29865154, 2018). "Stimulation of the renal cancer cell line A498 with EA results in an I/V curve with an outwardly rectifying shape for TRPC1/4, in contrast to the double rectifying shape observed for TRPC4α." (PMID 30108272, 2018). "Indeed, in our experiments, AC1903 inhibited multiple TRPC channels including TRPC3, TRPC4, TRPC5, TRPC6, TRPC4–C1, and TRPC5–C1, as well as endogenous TRPC1:C4 channels in A498 renal cancer cells, all with low micromolar IC50 values (1.8–18 μM)." (PMID 34999117, 2022). "Additionally, 100 μM histamine transiently activated currents with an outwardly rectifying I/V curve in the renal cancer A498 cells, which express TRPC1 and TRPC4." (PMID 30108272, 2018). "However, the highest potencies were measured against heteromeric channels (formed by TRPC4–C1 or TRPC5–C1 concatemers; IC50 values of 33 pM and 199 pM, respectively) and (−)EA-activated, endogenous TRPC1:C4 channels in A498 renal carcinoma cells (IC50 = 49 pM)." (PMID 29865154, 2018).
renal fibrosis (4 papers, 2020 to 2025). A final common manifestation of a wide variety of chronic kidney diseases characterized by glomerulosclerosis and tubulointerstitial fibrosis. "The deletion of circRNA_010383 promotes the expression of TRPC1 protein through the sponge of miRNA-135a, resulting in the formation of DN proteinuria, mesangial cell proliferation and renal fibrosis." (PMID 40526701, 2025). "miR-135a accelerates renal fibrosis through the regulation of TRPC1, which increases the synthesis of extracellular matrix proteins in diabetic kidney injury." (PMID 32617074, 2020).
Stroke (4 papers, 2020 to 2025). Sudden impairment of blood flow to a part of the brain due to occlusion or rupture of an artery to the brain. "TRPC1/3/4/6, TRPV1/2/4, and TRPM2/4/7 channels have been implicated in stroke pathophysiology." (PMID 36527242, 2023). "Since the TRPC4/C5 antagonists inhibit both TRPC4 or TRPC5 homomeric channels and TRPC1/C4 and TRPC1/C5 heteromeric channels, these data support the general idea that targeting TRPC1/C4/C5 channels can be beneficial to stroke therapy including post ischemic protection." (PMID 33490083, 2020). "However, a study oppositely found that TRPC1 shows a beneficial effect for stroke in mice." (PMID 41399206, 2025). "Recently, the Trpc1,4,5,6 quadruple KO mouse has also been assessed in the MCAO-reperfusion stroke model, with comparable (~50%) reduction in infarct volumes and again improved neurological deficit scores." (PMID 37462831, 2024). "The TRPC1/3/4/6, TRPV1/2/4, and TRPM2/4/7 channels have been extensively investigated focusing on their effects on neurons and gliocytes post‐stroke." (PMID 36527242, 2023).
Anxiety (3 papers, 2018 to 2025). Intense feelings of nervousness, tension, or panic often arise in response to interpersonal stresses. "In conclusion, this study suggests that TRPC1 plays a role in reversal learning and adaptability, as well as in other behavioral phenotypes, including anxiety and social interactions." (PMID 40777047, 2025). "Taken together, these results suggest that the inhibition of TRPC1 expression rescues the anxiety phenotype and the impaired social behavior of FXS mice." (PMID 40777047, 2025). "This proposed role of TRPC4/5 channels in fear behaviour has led to TRPC1/4/5 modulators being investigated as a possible treatment for anxiety." (PMID 29865154, 2018). "Studies of the roles of TRPC1/4/5 channels in anxiety, (−)EA-mediated cancer cell death and progressive kidney disease highlight the necessity and usefulness of small-molecule TRPC1/4/5 modulators for biological research." (PMID 29865154, 2018).
glaucoma (3 papers, 2023 to 2024). Increased pressure in the eyeball due to obstruction of the outflow of aqueous humor. "Other interesting druggable targets were two transient receptor potential cation channels, encoded by TRPC1, found upregulated in glaucoma lamina cribrosa cells and TRPM3." (PMID 39458974, 2024). "The TRPC1/C6 channels may constitute important therapeutic targets for preventing ECM remodeling and fibrosis progression in glaucoma optic neuropathy." (PMID 36674805, 2023). "Although there is currently no direct evidence linking STIM1/2 with glaucoma, TRPC1 and TRPC6 channels, which are known interacting partners of STIM isoforms, were upregulated in glaucomatous lamina cribrosa leading to NFAT4-mediated gene expression remodeling." (PMID 39424970, 2024).
Hepatic steatosis (3 papers, 2023 to 2024). Steatosis is a term used to denote lipid accumulation within hepatocytes. "Liver echogenicity in Trpc1−/− mice was increased as early as the 7th month of age compared to age-matched wild-type controls, consistent with hepatic steatosis." (PMID 38885005, 2024).
hypertrophic cardiomyopathy (3 papers, 2020 to 2024). A condition in which the myocardium is hypertrophied without an obvious cause. "Induced pluripotent stem cell-derived cardiomyocytes from hypertrophic cardiomyopathy patients exhibited diastolic dysfunction at the cellular level and increased expression of TRPC1." (PMID 36620209, 2022).
invasive ductal carcinoma (3 papers, 2016 to 2023). "Moreover increased expression of TRPC1 was observed in invasive ductal carcinoma, which is consistent with previous studies." (PMID 27793015, 2016). "Conversely, a significant increase (~30%) in TRPC1 expression was observed in the invasive ductal carcinoma (IDC) tissue samples, whereas no increase in actin (used as control) staining was observed." (PMID 27793015, 2016).
multiple myeloma (3 papers, 2017 to 2022). "The mechanism of action of this novel class of molecules includes the induction of cell death via calcium overload, a finding that was dependent on TRPC1/TRPC4/TRPC5 expression in multiple myeloma cell lines." (PMID 35804837, 2022). "Emergence of resistance to chronic exposure of increasing concentrations of MTI-101 in the multiple myeloma H929 cell line correlated with decreased expression of the IP3 receptor, SERCA pump, PLCβ, TRPC1, and TRPM7." (PMID 32046188, 2020).
myocardial infarction (3 papers, 2023 to 2025). Gross necrosis of the myocardium, as a result of interruption of the blood supply to the area, as in coronary thrombosis. "Endothelial cell-specific TRPC1 knock-out (KO) mice had lower EF and larger myocardial infarct size after left anterior descending (LAD) coronary artery ligation-induced myocardial infarction (MI)." (PMID 40366385, 2025). "In mice suffering from myocardial infarction (MI), it has been demonstrated that HIF-1α directly increases the expression of TRPC1." (PMID 40533673, 2025).
renal cell carcinoma (3 papers, 2017 to 2022). "TRPC1 is upregulated in various types of cancer, such as tongue, breast, gastric, ovarian, colorectal, and renal cell carcinoma, where its expression correlates with different clinical factors." (PMID 35887266, 2022). "Previous studies have suggested that A498 renal cell carcinoma cells contain endogenous EA-activated TRPC1/TRPC4 heteromeric channels." (PMID 28325835, 2017). "Transient receptor potential channel 1 (TRPC1) regulates the progression of several cancers, but its clinical implication in renal cell carcinoma (RCC) has not been explored yet." (PMID 35548183, 2022).